CIMIP6 (ciliary microtubule inner protein 6)
Synonyms: C2orf73; FLJ40298
Tractability: Antibody: the Human Protein Atlas places it where antibodies can reach.
Gene: Protein-coding gene on chromosome 2 (54,330,034 to 54,383,742, forward strand). Ensembl gene ENSG00000177994.
Subcellular location: Cell projection, cilium
Subcellular location (Human Protein Atlas): Nucleoplasm; Cytosol; Plasma membrane
Gene Ontology:
Cellular component: cilium
Genetic constraint (gnomAD): Loss-of-function variants: 18 observed, 12.81 expected, observed/expected ratio (o/e) 1.4, 90% interval 0.96 to 1.89. The upper end of that interval is the gene's LOEUF score, 1.89, which puts it in group 6 of 6, group 1 being the genes least tolerant of losing a copy. Missense variants: 280 observed, 239.54 expected, observed/expected ratio (o/e) 1.17, 90% interval 1.06 to 1.29. Synonymous variants: 103 observed, 83.82 expected, observed/expected ratio (o/e) 1.23, 90% interval 1.05 to 1.45.
Homologues: Orthologues: chimpanzee C2AH2orf73 (98% identical), macaque C13H2orf73 (92% identical), rabbit CIMIP6 (79% identical), dog C10H2orf73 (76% identical), pig CIMIP6 (73% identical), guinea pig CIMIP6 (63% identical), mouse Cimip6 (55% identical), rat C14h2orf73 (54% identical), tropical clawed frog cimip6 (36% identical).
Diseases named in the same sentence as CIMIP6 in open-access papers:
CIMIP6 is named in the same sentence as 4 diseases in open-access papers, as found by Europe PMC text mining. Sharing a sentence is not in itself a finding about the gene and the disease.
CIMIP6 shares sentences with these, for which no sentence is quoted: lymphoma (1 paper); neuroblastoma (1); pelvic organ prolapse (1); renal cell carcinoma (1).